KIFC1 (kinesin family member C1)
Diseases named in the same sentence as KIFC1 in open-access papers (continued):
Sharing a sentence is not in itself a finding about the gene and the disease.
seminoma (2 papers, 2017 to 2022). A radiosensitive malignant germ cell tumor found in the testis (especially undescended), and extragonadal sites (anterior mediastinum and pineal gland). "Our work here indicates that KIFC1 participates in facilitating proper division of seminoma cancer cells." (PMID 28977870, 2017). "We are the first to test and find out that KIFC1 is significantly enriched in seminoma tissue samples in both mRNA level and protein level." (PMID 28977870, 2017). "We then used western blot to quantify the endogenous protein expression level of KIFC1 among human muscle, testis and seminoma tissues." (PMID 28977870, 2017). "Specifically, in seminoma tissue, KIFC1 signal tends to be concentrated around the nucleus with less intense DNA." (PMID 28977870, 2017). "The high expression of KIFC1 in seminoma tissue indicates its possible importance, so we continued to explore the localization of KIFC1 of both seminoma and testis tissue samples." (PMID 28977870, 2017). "We found that KIFC1 is enriched in seminoma tissues in both mRNA level and protein level, and is specifically enriched in the cells that divide actively." (PMID 28977870, 2017). "KIFC1 is vastly distributed in both seminoma and testis tissue samples." (PMID 28977870, 2017). "So the first thing we did was to evaluate and compare the KIFC1 expression level in muscle, testis and seminoma tissue to determine whether KIFC1 is also important in testis cancer development." (PMID 28977870, 2017). "In both testis and seminoma tissues, KIFC1 and tubulin show obvious co-localization." (PMID 28977870, 2017). "Here we show that KIFC1 is also enriched in human seminoma tissues and might facilitate the proper division of seminoma cell division." (PMID 28977870, 2017). "This further indicates that KIFC1 must have unique role in seminoma cells." (PMID 28977870, 2017). "To this end, we conclude that KIFC1 might be essential in seminoma cell division." (PMID 28977870, 2017). "KIFC1 and KIF3B are enriched in tissues of human seminoma, one of the most frequent testis cancers affecting young men, with a role in cell division regulation in seminoma." (PMID 35547823, 2022). "There was no detectable KIFC1 expression in muscle tissues, and the KIFC1 protein level in seminoma tissues was also significantly higher than that in testis tissues." (PMID 28977870, 2017).
serous ovarian carcinoma (2 papers, 2014 to 2016). "To this end, we probed the publicly-available microarray dataset (GSE9899) and stratified the 154 serous ovarian adenocarcinoma patients from the dataset into KIFC1-high and KIFC1-low groups." (PMID 26992853, 2016). "To this end, we examined single channel microarray data from GEO and TCGA databases to compare KIFC1 gene expression levels in serous ovarian carcinoma to normal ovarian tissue." (PMID 25028599, 2014). "Also, gene expression levels of KIFC1 in high-grade serous ovarian carcinoma (HGSOC) highly correlated with expression of genes driving centrosome amplification (CA), as examined in publically-available databases." (PMID 26992853, 2016). "Interestingly, we found that the gene expression levels of KIFC1 were significantly higher in serous ovarian adenocarcinoma (n = 154) when compared to all other subtypes (Borderline serous adenocarcinoma, n = 18 and Peritoneal serous adenocarcinoma, n = 22)." (PMID 26992853, 2016). "Further, we examined grade-wise trends in KIFC1 expression in serous ovarian adenocarcinoma." (PMID 26992853, 2016).
adenoma (1 paper, 2012). A neoplasm arising from the epithelium. "Among them, EFNA1 had increased expression in carcinoma compared with adenoma, and KIFC1 had an upward trend but not significant in statistical analysis." (PMID 23158542, 2012).
Azoospermia (1 paper, 2016). Absence of any measurable level of sperm,whereby spermatozoa cannot be observed even after centrifugation of the semen pellet. "Robust KIFC1 immunnostaining was found in the round and elongating/elongated spermatids of obstructive azoospermia." (PMID 27690105, 2016). "Furthermore, we observed that KIFC1 was the most highly present in round and elongating/elongated spermatids, hardly expressed in pachytene spermatocytes, and undetected in spermatogonia and Sertoli cells of obstructive azoospermia." (PMID 27690105, 2016).
colon cancers (1 paper, 2021). "In this study, we demonstrated that KIFC1 was a biomarker of recurrence in human breast and colon cancers." (PMID 33397932, 2021).
colorectal tumor (1 paper, 2021). "In addition, the KIFC1 protein level was higher in colorectal tumor tissues than in paired peri-tumor specimens." (PMID 33397932, 2021). "Similarly, the KIFC1 protein level was positively correlated with colorectal tumor recurrence, but not with age and gender." (PMID 33397932, 2021).
COVID-19 (1 paper, 2023). A disease caused by infection with severe acute respiratory syndrome coronavirus 2. "In our study, seven genes (BUB1, PRC1, KIFC1, RRM2, CDKN3, CCNB2, and MCM6) were involved in the interaction between COVID-19 and silicosis." (PMID 37278873, 2023). "Finally, submodule analysis showed that PRC1, KIFC1, BUB1, MCM6, CCNB2, CDKN3, and RRM2, which were hub-shared genes of silicosis and COVID-19, possessed the highest mCODE scores." (PMID 37278873, 2023).
lentivirus infection (1 paper, 2025). Virus diseases caused by the Lentivirus genus. "SiRNA transfection and lentivirus infection were detected in PANC‐1 and SW‐1990 cells via western blotting, and the KIFC1 protein levels decreased and increased, respectively." (PMID 40857057, 2025).
leukemia (1 paper, 2024). A malignant (clonal) hematologic disorder, involving hematopoietic stem cells and characterized by the presence of primitive or atypical myeloid or lymphoid cells in the bone marrow and the blood. "For KIFC1 inhibitors, we found that both primary leukemia samples showed a higher sensitivity to AZ82 (3.5 μM, 3.9 μM) in comparison to Griseofulvin (20.2 μM, 54.4 μM) and CW069 (363.7 μM, 261.5 μM)." (PMID 38519798, 2024). "Further supporting a role for this pathway in Eμ-Ret leukemia progression, several proteins known to interact with KIFC1 were similarly upregulated in leukemia samples." (PMID 38519798, 2024). "As Eμ-Ret leukemia represents the emergence of a viable, consistently hyperdiploid cell population from a more numerically diverse aneuploid preleukemic cell pool, we hypothesized that KIFC1 would be enriched in leukemic samples." (PMID 38519798, 2024). "Therefore, we assessed the impact of KIFC1 inhibitors, as well as inhibitors of the mitotic kinases, aurora kinase A (AURKA) and polo-like kinase 1 (PLK1), on 2 primary Eμ-Ret leukemia samples and the 289 cell line." (PMID 38519798, 2024).
lymph node metastasis (1 paper, 2021). "KIFC1-positive cases were associated with high T stage and lymph node metastasis." (PMID 34768355, 2021).
meningioma (1 paper, 2019). A generally slow growing tumor attached to the dura mater. "To finally address the question, if differentially expressed kinesin family members have an impact on tumor cell proliferation of meningioma cells, we performed a siRNA-mediated knockdown of KIFC1, KIF4A, KIF11, KIF14 and KIF20A." (PMID 30991738, 2019). "Therefore, we re-analyzed our previous microarray dataset of benign, atypical, and anaplastic meningiomas (n = 62) and got evidence for differential expression of five kinesins (KIFC1, KIF4A, KIF11, KIF14 and KIF20A)." (PMID 30991738, 2019). "We demonstrated that KIFC1 mRNA and protein expression increased in meningiomas with the WHO grade." (PMID 30991738, 2019). "To query if kinesin family members might represent novel molecular therapeutic targets, we re-analyzed our previous microarray data set of benign, atypical and anaplastic meningiomas and identified five differentially expressed kinesins (KIFC1, KIF4A, KIF11, KIF14 and KIF20A)." (PMID 30991738, 2019). "This analysis revealed that high levels of KIFC1 (p = 0.04; HR 1.84), KIF11 (p = 0.03; HR 1.88), KIF14 (p = 0.03; HR 1.91) and KIF20A (p = 0.01; HR 2.13) were associated with a shorter progression-free survival, suggesting kinesins as novel prognostic factors in meningiomas." (PMID 30991738, 2019). "Therefore, we used ten meningioma tissue samples for each WHO grade and stained them for KIFC1, KIF4A, KIF11, KIF14 and KIF20A." (PMID 30991738, 2019).
neuroblastoma (1 paper, 2023). Neuroblastoma (NB) is the most common solid, extracranial childhood tumor. "To investigate the effect of MYCN on mitotic dysregulation and its functional consequences in neuroblastoma cells, we performed siRNA knockdown of AURKB, BUB1, and KIFC1 in MYCN-regulable SHEP21N cells." (PMID 37958555, 2023). "To assess the functional requirement of mitotic genes in established neuroblastoma, we next quantified the effect of silencing two representative genes within the MSG in neuroblastoma cell lines, BUB1 and KIFC1." (PMID 37958555, 2023).
oral squamous cell carcinoma (1 paper, 2025). "Whilst no DUBs have previously been reported to regulate KIFC1, candidates from genome-wide screens for centrosome clustering regulators in Drosophila or oral squamous cell carcinoma, included orthologs of USP8 (CG5798) and USP43 (CG30421) and the pseudo-DUB USP54." (PMID 39789388, 2025).
rectal cancer (1 paper, 2012). A primary or metastatic malignant neoplasm that affects the rectum. "Copy number increase of EFNA1 (1q22), PTGS2 (1q31.1), KDM5B (1q32.1), ESRRG (1q41), KIFC1 (6p21.32), PBX2 (6p21.32) and SOX4 (6p22.3) were only detected in rectal cancer in array CGH." (PMID 23158542, 2012).
rectal tumor (1 paper, 2012). "Of these genes KIFC1 and SOX4 were also significantly overexpressed in rectal tumor tissues than paracancerous tissues." (PMID 23158542, 2012).
silicosis (1 paper, 2023). Silicosis is a respiratory disease caused by breathing in (inhaling) silica dust. "In the rat model exposed to silica inhalation for 4 weeks, Bub1, Kifc1, Mcm6, and Prc1 were upregulated in the silicosis group, while Cdkn3 was downregulated." (PMID 37278873, 2023).
soft tissue sarcoma (1 paper, 2024). A malignant neoplasm arising from muscle tissue, adipose tissue, blood vessels, fibrous tissue, or other supportive tissues excluding the bones. "This study elucidates the oncogenic role of KIFC1 in soft tissue sarcoma (STS) and provides the first evidence that targeting KIFC1 induces cellular senescence via interacting with FXR1, thereby stabilizing MAD2L1 mRNA in an m6A‐dependent manner." (PMID 39387242, 2024).
testis cancer (1 paper, 2017). "Meanwhile, KIFC1 is also found to be enriched in numerous of cancer types, but there is no report on testis cancers." (PMID 28977870, 2017). "However, the gene expression profiles of testis cancer is still not complete and the expression of the C-terminus kinesin motor KIFC1 in testis cancer has not yet been examined." (PMID 28977870, 2017).
cancer (91 papers, 2010 to 2026). A tumor composed of atypical neoplastic, often pleomorphic cells that invade other tissues. "Kinesin-14 family protein 1 (KIFC1) is abnormally overexpressed in various cancers, and the transcription factor ETS variant 1 (ETV1) is an oncogenic transcription factor in tumors." (PMID 40612867, 2025). "With respect to KIFC1, growing evidence suggests that KIFC1 overexpression is strongly associated with cancer development, progression and drug resistance." (PMID 40857057, 2025). "TACC3 and ch-TOG have previously been shown to be involved in centrosome clustering in cancer cells, either via interaction with integrin-linked kinase or with KIFC1." (PMID 40105698, 2025). "KIFC1 overexpression is associated with poor clinicopathological characteristics in various malignant tumors." (PMID 40612867, 2025). "Single-cell analysis also revealed that MCM4-expressing cells were located upstream of the trajectory, with a cluster showing a correlation with KIFC1, which has been reported to be associated with cancer stemness." (PMID 40293517, 2025). "Overall, these findings provide insights into the potential biological functions of KIFC1, highlighting its involvement in critical cellular processes and association with cancer." (PMID 38457554, 2024). "It is noteworthy that aberrations in the expression levels of KIFC1 have been demonstratively linked with progression in specific categories of cancer." (PMID 37955677, 2023). "In summary, these results indicate that higher expression of KIFC1 is linked to growth regulation in various cancers and offer insights for further investigation into the functions and roles of KIFC1 in cancer initiation and progression." (PMID 38112634, 2023). "The heatmap analysis of KIFC1 in pan-cancer demonstrated a strong association between KIFC1 and the prognosis of most cancers." (PMID 38112634, 2023). "Reportedly, KIFC1, a Kinesin-14 motor protein, has been implicated in the process of centrosome clustering, whereby cancer cells aggregate their excess centrosomes into pseudo-bipolar spindles to facilitate progression through the cell cycle." (PMID 38112634, 2023). "KIFC1, which encodes a kinesin motor known to have a role in the clustering of the centrosomes of cancer cells, is involved in several types of cancers." (PMID 36945359, 2023). "GSEA was performed using the differentially expressed genes (DEGs) between low- and high-KIFC1 subgroups in each cancer to identify the cancer hallmarks associated with KIFC1." (PMID 38112634, 2023). "To explore the relationship between KIFC1 and cancer immunity, we investigated the association between KIFC1 expression and immune cell infiltrations." (PMID 38112634, 2023). "KIFC1 is essential for supernumerary centrosomes, and it is associated with the initiation and progression of cancers." (PMID 35327439, 2022). "KIFC1 has also been shown to be associated with the initiation and/or progression of a variety of cancers." (PMID 35327439, 2022). "A Kaplan-Meier analysis showed that the KIFC1-positive cases were significantly associated with poor cancer-specific survival (hazard ratio 6.443, p < 0.001) and overall survival in BC (hazard ratio 3.159, p < 0.001) in the Hiroshima cohort." (PMID 34768355, 2021). "Overall, high KIFC1 mRNA expression was associated with lower recurrence-free survival in PCa as well as other cancer types, indicating that patients with these cancer types and high KIFC1 levels have a poorer prognosis." (PMID 33760984, 2021). "Several studies have shown that KIFC1 is associated with an apoptosis pathway, and inhibition of KIFC1 suppresses cell proliferation, but also induces the apoptosis pathway in different cancer cells." (PMID 31895691, 2019). "To further illustrate KIFC1’s role in cancer cells, we continued to explore the loss-of-function of KIFC1 while cell division." (PMID 28977870, 2017).
cancer (continued). "Kinesin family member C1 encoded by KIFC1, plays an essential role in centrosomal bundling in cancer cells, and has been suggested as a potential therapeutic target." (PMID 27341628, 2016). "Recently several studies have shown that knockdown of KIFC1 in cancer cell lines containing supernumerary centrosomes causes the excess centrosomes to be scattered by pole-separating forces that induce spindle multipolarity and cell death." (PMID 26992853, 2016). "Recently, supernumerary centrosomes and high KIFC1 expression have been associated with chromosome missegregation that results in low-grade aneuploidy, a landmark of cancers." (PMID 25028599, 2014). "On the contrary, KIFC1 has been implicated in the pathogenesis of various cancer types." (PMID 39074902, 2024). "Additionally, Disease Ontology (DO) term annotation analysis revealed an association between KIFC1 and cancer." (PMID 38457554, 2024). "Hence, we first analyzed the landscape of genetic alterations such as mutation, structural variant, amplification, and deep deletion in the KIFC1 gene using the TCGA cancer datasets through the cBioPortal tool." (PMID 38112634, 2023). "Hence, we observed the link between TMB/MSI and KIFC1 expression in pan-cancer, and we found that KIFC1 was positively associated with TMB in most cancers while negatively linked with TMB in THYM." (PMID 38112634, 2023). "Indeed, AZ82 is a small molecular inhibitor of KIFC1, and it causes centrosome declustering in cancer cells." (PMID 35327439, 2022). "Additionally, high KIFC1 levels are associated with poor recurrence-free survival in PCa as well as other cancer types." (PMID 33760984, 2021). "Furthermore, we developed a potential centrosome abnormality biomarker applicable to routinely fixed paraffin-embedded tumor tissue to enable patient segmentation of those with cancers susceptible to KIFC1/centrosome amplification targeted therapy." (PMID 29535384, 2018). "The loss-of-function of KIFC1 in cancer cells renders a lowered proliferation rate, indicating that KIFC1 might be essential in proper cancer cell division." (PMID 28977870, 2017). "Due to its promotion of several oncogenic phenotypes and the dependence of cancer cells on KIFC1 to avoid the deleterious effects of CA-associated multipolar mitotic spindles, KIFC1 is a promising target in cancers in which CA is prevalent." (PMID 40002279, 2025). "Additionally, KIFC1 expression levels have been shown to influence immune cell infiltration within tumor microenvironments, as well as being closely associated with tumor mutation burden and microsatellite instability in multiple cancer types." (PMID 38112634, 2023). "Taken together, these data suggest a potential oncogenic role for OTUD6B and support the idea that OTUD6B maintains KIFC1 protein levels in cancer cells." (PMID 39789388, 2025). "Together, these findings highlight OTUD6B as a DUB that maintains KIFC1 levels to ensure supernumerary centrosomes remain clustered, allowing cancer cells to avoid mitotic catastrophe and complete cell division." (PMID 39789388, 2025). "KIFC1 (Kinesin family member C1) contributes to centrosome integrity, and its knockdown has been shown to suppress cancer cell proliferation." (PMID 41246267, 2025). "KIFC1 is highly expressed in many cancers at both the RNA and protein levels, including breast, ovarian, bladder, prostate, and kidney tumours, among others." (PMID 40002279, 2025). "As a deubiquitinase that supports KIFC1 expression, allowing pseudo-bipolar cell division and survival of cancer cells with centrosome amplification, OTUD6B has potential as a novel target for cancer-specific therapies." (PMID 39789388, 2025). "Coincidentally, KIFC1 can aggregate centrosomes to achieve bipolar division of cancer cells, promoting their survival and proliferation." (PMID 40857057, 2025).